ANXA1 (annexin A1)
Diseases named in the same sentence as ANXA1 in open-access papers (continued):
Sharing a sentence is not in itself a finding about the gene and the disease.
cancer (continued). "Previous studies shown that expression of ANXA1 is increased in certain cancers such as pancreatic and gastrointestinal cancer, and decreased in others such as esophageal and prostate cancer." (PMID 29263330, 2017). "Taken together, these findings along with ours suggest the potential role of ANXA1 in cancer development and progression." (PMID 29091952, 2017). "This does not exclude the targeting of other gene products with a potential role in the transcriptional repression of ANXA1 promoter activity and independent effects on the cancer phenotype." (PMID 28754915, 2017). "Changes in the expression of ANXA1 have been reported in various cancers and, furthermore, its expression has been compared to that of other proteins." (PMID 27209356, 2016). "The extracellular form of ANXA1 has been as well described to stimulate cell motility and cancer cell invasion capability, mostly interacting with specific receptors." (PMID 26312765, 2015). "To better understand the role of ANXA1 in cancer of the oropharynx, we evaluated the expression of its phosphorylated forms in the tissues studied." (PMID 24782913, 2014). "YG participated in the design of the study, carried out the mRNA and protein expression of ANXA1 in human tissues and cancers and analyzed the data." (PMID 25038797, 2014). "The extracellular form of ANXA1 has been as well described to play a role in cancer cell invasion and metastasis." (PMID 25510623, 2014). "The expression of ANXA1 was increased in certain cancers such as pancreatic cancer, and gastrointestinal cancer and decreased in others such as esophageal and prostate cancer." (PMID 25536365, 2014). "Once again, this provides good insight into understanding the role of ANXA1 in cancer initiation and progression." (PMID 25536365, 2014). "ANXA1, a protein related to inflammatory response and involved in cell proliferation, has been studied in various cancers with contrasting findings." (PMID 24782913, 2014). "The aim of our study is to investigate the role of ANXA1 in human PC progression, in particular we focused on its involvement in cancer cell migration and invasiveness." (PMID 25510623, 2014). "The extracellular form of ANXA1 has been described to play a role in cancer cell invasion and metastasis." (PMID 25510623, 2014). "Although ANXA1 is attracting more attention in cancer research, the conflicting reports on the expression of ANXA1 limited its importance as a therapeutic and/or prognostic biomarker in cancer." (PMID 25038797, 2014). "Of these proteins, only 3 were considered to be potential biomarkers for carcinomas: stathmin (increased expression), 14-3-3ϭ (reduced expression), and ANXA1 (reduced expression)." (PMID 24782913, 2014). "In the present study, we determined that the expression of ANXA1-SER was increased in the normal epithelia compared to carcinomas in the HPV + cases." (PMID 24782913, 2014). "This study demonstrated an increase in ANXA1 expression in HPV + carcinomas compared to the expression detected in HPV- carcinomas." (PMID 24782913, 2014). "Our results support a significant correlation between NaB functions and ANXA1 expression in prostate cancer, and pave the way for further studying the molecular mechanism of NaB actions in cancers." (PMID 24086397, 2013). "Taken together, the results indicated that Anxa1 expression is highly tissue specific in different cancers." (PMID 23991102, 2013). "A great deal of controversy still exists regarding the expression of ANXA1 in different types of cancers." (PMID 24086397, 2013). "ANXA1, the first member of the family of annexins, is an intracellular protein which plays important roles in apoptosis, proliferation, and cancer." (PMID 24086397, 2013). "Our results pointed out the significant up-regulation of ANXA1 in all type of cancer respect to control." (PMID 24023790, 2013).
cancer (continued). "The results obtained for ANXA1 and p16 using qPCR were in agreement with the RaSH method, providing further evidence that these genes are cancer-related." (PMID 23341933, 2013). "The ERK pathway is frequently up-regulated in a variety of cancers, and there is some evidence showed that ANXA1 modulates the ERK pathway at a proximal site." (PMID 24086397, 2013). "Annexin A1, a major substrate for epidermal growth factor receptor kinase, plays an important role in cancer development and progression." (PMID 23890079, 2013). "On the other hand, there is also some evidence that an increase of ANXA1 expression has occurred in other types of cancer, such as pancreatic, esophageal, and gastric carcinomas." (PMID 24086397, 2013). "The dysregulation of the annexin family members including annexin A1, A2, A5, A6, A7, A8, and A9, among others, were reported in numerous cancers." (PMID 22929401, 2012). "A number of theories on the possible signal pathway of annexin A1 in cancer development are available." (PMID 22929401, 2012). "Although ANXA1 has predominantly been studied in the context of immune responses and cancer, the protein can affect a larger variety of biological phenomena, including cell proliferation and migration." (PMID 23144744, 2012). "We performed Western blot to confirm the differential expressions of Hsp90-beta and annexin A1 and to verify their differential expressions in the matched cancer tissues and adjacent normal tissues." (PMID 22929401, 2012). "Annexin A1 expression has been shown to be down regulated in several cancers such as esophageal, prostate, breast, and larynx cancers." (PMID 22929401, 2012). "The relative expression of ANXA1 in the CD26+ cancer cells vs. luminal cells was also decreased in G4 compared to G3, whereas relative IL6 expression was increased." (PMID 20021671, 2009). "By immunohistochemistry annexin A1 was noted in the vascular environment in cancer and certain precancerous samples." (PMID 18637184, 2008). "In this study we have demonstrated that there is a trend toward upregulation of the tyrosine modified proteins, Annexin A1, DNA-PKcs and certain calcium binding proteins in cancer specimen in contrast to normal." (PMID 18637184, 2008). "Annexin A1 was identified by MALDI-TOF MS after in gel trypsin digestion to be differentially expressed in cancer samples compared to controls when 2D gels were compared." (PMID 18637184, 2008). "Another protein that was noted to be modified by tyrosine phosphorylation in cancer as well as in precancerous states and also shown to co-immunoprecipitate with annexin A1 is DNA-PKcs." (PMID 18637184, 2008). "We found that cancer.cell. communicated with CD8_ANXA1, Mono_EREG, CAF_C3, and Fibrocyte_CD34, which further identified that cancer.cell. might be an immune-escaped cell cluster." (PMID 40725006, 2025). "The results revealed strong interactions between cancer.cell. and Mono_EREG, CD8_ANXA1." (PMID 40725006, 2025). "Further research, including validation of its protein expression in cancer cell lines or tissue biopsy samples, is necessary to fully explore its role and to determine whether targeting ANXA1 could enhance the efficacy of immunotherapies." (PMID 40744683, 2025). "Our data show that the ANXA1 cytokine may play a vital and bimodal role in cancer cell death and survival under oxidative stress." (PMID 40520087, 2025). "The aim of several recent studies has been the assessment of ANXA1’s therapeutic value in cancer." (PMID 41283264, 2025). "Additionally, ANXA1 is associated with EMT, a process crucial for cancer cells to acquire invasive and migratory capabilities." (PMID 40744683, 2025). "Furthermore, the aim of the present study was to investigate ANXA1’s biological activity on two different OSCC HPV- cancer cells from the tongue, also in correlation with its overexpression induced by 5-AZA, in terms of cell motility and phenotypic changes." (PMID 40227604, 2025).
cancer (continued). "Previous studies have reported ANXA1 as a double-edged cytokine responsible for inhibiting inflammation, promoting apoptosis or cell proliferation and facilitating cell migration/wound healing depending on the cancer cell type." (PMID 40520087, 2025). "ANXA1 is a phospholipid-binding protein that regulates cancer cell proliferation and metastasis." (PMID 40018643, 2025). "However, we excluded the classical mechanisms of ANXA1 involved in cancer progression reported in previous studies, such as the signal pathways of MAPK, NF‐κB, Hippo, and TGF‐β." (PMID 39447086, 2024). "MTT assays were used to determine whether MDX-124 could induce a functional anti-proliferative response across the panel of cancer cells by targeting ANXA1." (PMID 38200229, 2024). "Additionally, the endogenous PLA2 inhibitor, Annexin A1, plays a role in cancer progression, contributing to the suppression of the immune response, and indicating cancer aggressiveness." (PMID 39596471, 2024). "The purpose of this study was to determine whether MDX-124, a humanised monoclonal antibody targeting ANXA1, could impact cancer cell growth using in vitro and in vivo models." (PMID 38200229, 2024). "In this present study we show that targeting ANXA1 with the humanised monoclonal antibody, MDX-124, can reduce cell growth in ANXA1-expressing cancer cells both in vitro and in vivo, providing further evidence that ANXA1 is a valid target for therapy in cancer." (PMID 38200229, 2024). "Among 12 annexin A isoforms (annexin A1-11 and annexin A13), annexin A5 in particular has unphosphorylated short N-terminus which enables this protein to exhibit a wide range of functions such as signalling, cancer cell growth, and invasion." (PMID 38249992, 2024). "In contrast, in carcinomas, ANXA1 expression gradually increases as lesions approach malignant transformation to allow and promote the transformation of fibroblasts into CAFs (enhanced by increased TGF-β production), thereby driving malignancy possibly through FPR activation." (PMID 38645221, 2024). "Protein levels of ANXA1 were assessed in the MCF-7 cancer cell line using Western blot analysis." (PMID 37507468, 2023). "Similarly to phosphoglycerate kinase 1, annexin A1 can take part in a wide variety of cancer processes, including carcinogenesis, cell proliferation, invasion, apoptosis, and metastasis." (PMID 37834061, 2023). "Annexin A1 (ANXA1) is a ligand of FPR1 relevant for cancer immunosurveillance." (PMID 37555363, 2023). "ANXA1 expression was related to the 14 functional states in nine cancer types." (PMID 37434432, 2023). "Several cancer related pathways were found to be enriched in the high ANXA1 group." (PMID 37735492, 2023). "Annexin A1 (ANXA1) modulates cancer cell proliferation, apoptosis, invasion, and metastasis." (PMID 37067729, 2023). "However, in our experimental setting, only annexin A5 showed consistently higher binding to cancer cell-derived m/lEVs (annexin A1+)." (PMID 36992223, 2023). "This might be especially interesting in PC, as it could be shown that a binding of NF-кB to the DNA might be prevented in PC cell lines due to induction of ANXA1, which increases apoptosis and harms proliferation of these cancer cells." (PMID 37239137, 2023). "P50479 (PDLIM4) together with P04083 (ANXA1) could distinguish benign nodule from malignant nodule, and the AUC was as high as 1.00." (PMID 36418670, 2023). "The overall findings of this study may pave the way for future research aimed at harnessing the therapeutic benefits of BF in the context of ANXA1-mediated pathways in cancer." (PMID 37507468, 2023). "The same group also explored expression patterns of Annexin A1 and Annexin A2, two structurally and phylogenetically related proteins, in tissue specimens from respiratory (nasal and laryngeal) and digestive (oral and pharyngeal) mucosa of non-cancer patients." (PMID 35563776, 2022). "It is clear that expression of ANXA1 between different cancers is variable." (PMID 35146757, 2022).
cancer (continued). "The protective anti-inflammatory action of ANXA1 has since been demonstrated in several models, including arthritis, heterologous skin transplantation, cancer, eye allergy, heart failure, lung injury, nonalcoholic steatosis, myocardial infarction, and skeletal muscle injury." (PMID 35805141, 2022). "Besides, many other DAMPs such as type I IFN, annexin A1, cancer cell-derived nucleic acids, heat shock protein 90 (HSP90), and HSP70 are associated with ICD." (PMID 35409302, 2022). "ANXA1 has also been shown to play a role cancer progression through interactions with immune cells." (PMID 35146757, 2022). "ANXA1 knockdown has also shown to suppress the proliferation, migration and invasion of non‐small‐cell lung cancer cells and has been suggested as an in vitro therapeutic target in this form of cancer." (PMID 35146757, 2022). "Furthermore, ANXA1 N-terminal mimetic peptide Ac 2–26 has been proposed as a potential therapeutic strategy for cancer treatment, targeting ANXA1-mediated functions and related signaling pathways." (PMID 36247003, 2022). "We next explored the signaling pathways which could be involved in the ANXA1-dependent crosstalk between metastatic cancer cells and microglial cells." (PMID 35382852, 2022). "It has been found that ANXA1 is closely related to many types of malignant tumors, and it may be involved in the occurrence and development of VS tumors." (PMID 36304995, 2022). "In addition to mediating the inflammatory process, ANXA1 is involved in important pathophysiological processes, including cell proliferation and differentiation, cancer, and apoptosis; many of these processes relate to the response to DNA damage." (PMID 35805141, 2022). "It is worth highlighting that ANXA1 and ANXA2 have been linked to radio-chemoresistance and immunosuppression in HNC and other cancers, which poses a plausible application as adjuvant treatments to jointly improve treatment response and antitumor immune response." (PMID 36247003, 2022). "The role of ANXA1 has been extensively investigated in cancer cells." (PMID 35604142, 2022). "However, there is an increasing evidence that ANXA1 can play a role in disease, including inflammatory disease and cancer progression." (PMID 35146757, 2022). "ANXA1 has been related to treatment resistance in several cancers." (PMID 36247003, 2022). "As anticipated, ANXA1 bestows upon 4T1 cancer cells, the ability for microglial recruitment." (PMID 35382852, 2022). "In several cancer types, ANXA1 is involved in processes regulating increased invasiveness and EMT." (PMID 36077674, 2022). "Similarly, ANXA1 promotes the development of blood vessels and metastasis with a deleterious effect in cancer, however positive effects during the WH process." (PMID 34446793, 2021). "Moreover, changes in the behavior of the endogenous PLA2 inhibitor, the protein Annexin A1 (AnxA1), contribute to cancer progression." (PMID 34208346, 2021). "Recently, AnxA1 has been described to play immunosuppressive roles in the cancer context." (PMID 34208346, 2021). "ANXA1 also promotes the proliferation and metastasis of cancer cells through the binding of EphA2, the suppression of autophagy and the activation of the PI3K/AKT pathway and promotes proliferation and migration via the regulation of the IL-6/JAK2/STAT3 pathway." (PMID 34439260, 2021). "The effect of miR-196a is rescued by over-expressing ANXA1, which may also suggest that the functional role of miR-196a in cancer may be tissue- and cell type- specific." (PMID 34803496, 2021). "In fact, AnxA1 cleavage could explain why corticosteroids can display a pro-tumoral or an anti-tumoral effect depending on the type of cancer." (PMID 34208346, 2021).
cancer (continued). "Besides AnxA1 being widely described for its anti-inflammatory activities, its role in cancer development and progression stands out." (PMID 34571894, 2021). "Therefore, AnxA1 can promote the release of PLA2-enriched exosomes from cancer cells, leading to increased PGE2 levels and subsequently to an increase in the inflammatory response and immunosuppression in TME." (PMID 34208346, 2021). "Therefore, it is possible to draw some future perspectives for cancer treatment that involve the inhibition of AnxA1 signaling." (PMID 34571894, 2021). "Moreover, Annexin A1 promotes the release of cancer-derived exosomes, which also lead to the enrichment of PLA2 and COX-1 and COX-2 enzymes, contributing to TME formation." (PMID 34208346, 2021). "In addition, ANXA1 is highly expressed in different cancers, such as hepatocellular carcinoma, lung cancer, and colorectal cancer." (PMID 34484309, 2021). "Additionally, in the first case, the authors demonstrated the involvement of annexin A1 signaling suppressed by Pug, whereas in glioma cancer cells Pug treatment led to cell death through the activation of AMPK route." (PMID 34444893, 2021). "Similarly, the expression of the ANXA1/FPR1 or FPR3 pair was upregulated from ductal cell-myeloid cell to cancer cell-myeloid cell communication." (PMID 34326696, 2021). "In this report, OOC experiments in humans and mouse settings were crucial to demonstrate the importance of the integrity of the FPR1/Anxa1 axis to allow immune cell migration and interaction with cancer cells undergoing chemotherapy-induced immunogenic cell death." (PMID 33842539, 2021). "In addition, in tumors, ANXA1 levels and activity differ depending on the distinct tissue, and it is positively involved in cancer progression." (PMID 34681678, 2021). "Meanwhile, in promoting cancer phenotypes, ANXA1 performs versatile functions." (PMID 33959206, 2021). "Several mechanisms have been observed regarding the role of ANXA1 in cancer metastasis." (PMID 34439260, 2021). "The role of Annexin A1 has been extensively studied in a number of cancers and tumors cell lines." (PMID 34943928, 2021). "The anticancer immune response of ICD is contributed by the release of damage-associated molecular pattern molecules (DAMPs) by dying cancer cells and stressed cancer cells, such as high-mobility group box 1 (HMGB1), heat shock protein 70 (Hsp70), ATP, annexin A1 (ANXA1), and calreticulin (CRT)." (PMID 33799527, 2021). "Indeed, cancer cells treated with anthracyclines (i.e., Doxorubicin or Mitoxantrone) release Anxa1, which acts as a danger signal for immune cells." (PMID 33842539, 2021). "Interestingly, we found that ANXA1 is positively correlated to the apoptosis pathway, where evading apoptosis is one of the original hallmarks of cancer." (PMID 33804148, 2021). "In addition to AnxA1 expression and signaling pathways, its cellular localization has been demonstrated to be relevant in the cancer context." (PMID 34571894, 2021). "Annexin-A1 (ANXA1) could be one of these targets as ANXA1-containing EVs are found to be elevated in the serum of various cancer patients, and ANXA1 was heavily reported to be involved in PC invasion and metastases processes." (PMID 34207163, 2021). "Moreover, Annexin A1 (AnxA1) is also a candidate regulator of oncogenic switch during which cancer cells change their phenotype from epithelial to migratory, mesenchymal-like." (PMID 33593445, 2021). "The role of AnxA1 in angiogenesis has been shown in different models of cancer." (PMID 32403233, 2020). "Furthermore, it has been found that in different cancer cells including PC cells, ANXA1 is released in both full-length and truncated forms, after having undergone post-transductional modifications." (PMID 33353163, 2020). "However, it has now been recognized that ANXA1 also has important implications in maintaining homeostasis, fetal development, aging processes and in the evolution of several diseases such as cancer." (PMID 32887260, 2020).